PIR (pirin)
Diseases named in the same sentence as PIR in open-access papers (continued):
Sharing a sentence is not in itself a finding about the gene and the disease.
Alzheimer disease (2 papers, 2023 to 2024). A progressive, neurodegenerative disease characterized by loss of function and death of nerve cells in several areas of the brain leading to loss of cognitive function such as memory and language. "For examples, by high throughput technologies, the upregulation of piR‐hsa‐22564 and piR‐hsa‐14621, the downregulation of piR‐hsa‐14962 may be correlated with the increased risk of Alzheimer's disease." (PMID 39228010, 2024). "Various neurodegenerative conditions, including Alzheimer’s disease, motor neuron disease, Parkinsonism, Ramsay Hunt paralysis syndrome and amyotrophic lateral sclerosis (Guam form) are enriched for Pirin and its partnering proteins." (PMID 38033031, 2023).
asthenozoospermia (2 papers, 2021 to 2022). "An analysis revealed 17 piRNAs with a more-than-twofold decrease, to which piR-1207 and piR-2107 were significantly downregulated in asthenozoospermia patients." (PMID 36555356, 2022). "Consistent with the results from deep sequencing, piR-1207 and piR-2107 levels were markedly downregulated in sperm of asthenozoospermia patients." (PMID 34326815, 2021). "Among the significantly upregulated piRNAs, piR-26951 was predicted to target transcripts encoding flagella-associated protein 45 (CFAP45) and bromodomain-containing protein 2 (BRD2), both found to be differentially expressed in the sperm of patients with asthenospermia." (PMID 36555356, 2022).
bladder cancer (2 papers, 2020 to 2022). "The results showed that in bladder cancer tissues, 106 piRNAs were found to be up-regulated whereas 91 were down-regulated with piRNADQ594040 (piRABC and piR-60152) related to bladder cancer had the highest down-regulation fold change." (PMID 36733811, 2022). "The abnormal high expression of piR-594040 was found in bladder cancer." (PMID 32881713, 2020).
Cirrhosis (2 papers, 2018 to 2021). A chronic disorder of the liver in which liver tissue becomes scarred and is partially replaced by regenerative nodules and fibrotic tissue resulting in loss of liver function. "More interestingly, since cirrhosis and chronic hepatitis are often considered precancerous lesions of HCC, and the expression of piR-Hep1 in these lesions is higher than normal liver tissues, the elevated piR-Hep1 levels may indicate the risk to develop liver cancer in an individual." (PMID 35008366, 2021).
colon cancer (2 papers, 2018 to 2024). "We found that the sizes and numbers of colon tumors in PIR‐knockout mice were remarkably lower than in wild‐type mice." (PMID 38148593, 2024). "The role of PIR in colon cancer development was then investigated in a well‐established colitis‐associated colorectal tumor model." (PMID 38148593, 2024). "Here it is demonstrated that the upregulation of pirin (PIR) protein in colon cancers promotes tumorigenesis." (PMID 38148593, 2024). "Consistently, Western blot analysis showed an increase expression of p‐NFκB2, NIK, and FAS in the colon tumors of PIR‐knockout mice as compared with wild‐type mice." (PMID 38148593, 2024). "To this effect, we performed several functional assays to determine phenotypic alterations following overexpression or inhibition of piR-1245in colon cancer cells." (PMID 29382334, 2018). "Moreover, PIR was highly expressed in colon cancer cell lines and rarely expressed in normal cell lines MEF and HFF." (PMID 38148593, 2024). "This investigation reveals a suppressive immune landscape in PIR‐high and FAS‐low expression human colon cancer." (PMID 38148593, 2024). "Furthermore, FAS is negatively correlated with PIR, and positively correlated with NFκB2 and NIK in 54 paired colon cancer patient samples." (PMID 38148593, 2024). "Moreover, we analyzed a set of colon cancer cell lines from GEO database (GSE28567) and also found negative correlation of FAS with PIR and positive correlation with NFκB2 and NIK." (PMID 38148593, 2024).
colorectal tumor (2 papers, 2022 to 2024). "We determined the gene expression of pirin in 48 primary human colorectal tumours and matched normal tissue from the same patients." (PMID 35204145, 2022). "We then addressed the potential functional consequences of the observed pirin upregulation in colorectal tumours." (PMID 35204145, 2022). "Moreover, pirin is overexpressed in human colorectal tumours where pirin expression correlates with Nrf2 activation, suggesting Nrf2 dependence." (PMID 35204145, 2022). "Furthermore, we found that pirin is overexpressed in human colorectal tumours, and this overexpression correlates with Nrf2 activation." (PMID 35204145, 2022). "Knockout or inhibition of PIR dramatically increases FAS expression, FAS‐dependent apoptosis and attenuates colorectal tumor formation in mice." (PMID 38148593, 2024).
COVID-19 (2 papers, 2021 to 2023). A disease caused by infection with severe acute respiratory syndrome coronavirus 2. "Variants in the PIR gene have been linked to interethnic disparities in COVID-19 case fatality rates." (PMID 38033031, 2023). "Variants with inverse correlation with COVID-19 cases include a variant in ABO which increases the expression of its transcript, and the two unrelated variants in ACE2 which may potentially increase the expression of PIR mRNA in both lung and blood." (PMID 33981715, 2021).
diabetes (2 papers, 2014 to 2016). "It was notable that the pIGF1R/pIR glandular cell staining localizations differed for the diabetes (cytoplasmic staining) and OC use (nuclear staining) results." (PMID 27125830, 2016).
endometrioid ovarian cancer (2 papers, 2021 to 2022). "piR-52,207 and piR-33,733 promote endometrioid ovarian cancer and serous ovarian cancer cell proliferation, migration, and tumorigenesis respectively." (PMID 35715825, 2022). "Specific findings showed that piR-52207 was upregulated in endometrioid ovarian cancer, and piR-52207 and piR-33733 were increased in serous ovarian cancer." (PMID 33802524, 2021). "Upregulated piR-52207 targets NUDT4, MTR, EIF2S3, and MPHOSPH8, which promote endometrioid ovarian cancer cell proliferation, migration, and tumorigenesis." (PMID 33802524, 2021).
invasive breast carcinoma (2 papers, 2013 to 2021). A carcinoma that infiltrates the breast parenchyma. "The frequency and levels of PIR expression was similar between non-cancerous and invasive breast cancer tissues." (PMID 23374458, 2013).
multiple myeloma (2 papers, 2021 to 2026). "Moreover, in multiple myeloma cell lines, the silencing of piR-004800 induces apoptosis in vitro and in vivo." (PMID 34118972, 2021). "The cooperation of downregulated piR-004800 and the PI3K/AKT/mTOR signaling pathway restrains cellular growth in exosomes from bone marrow supernatants of patients with multiple myeloma." (PMID 34118972, 2021).
oral cancer (2 papers, 2020 to 2023). "Our results demonstrate a new mechanism by which E7 contributes to oral cancer progression, proposing PIR as a potential new therapeutic target." (PMID 32679705, 2020). "Furthermore, high-risk human papillomavirus (HR-HPV) oncoproteins enhance levels of Pirin in both epithelial cervical and oral cancer cells." (PMID 38033031, 2023). "Here, we addressed the role of signaling pathways involved in HPV16 E7-mediated PIR/NF-κB activation and oral cell migration, finding that HPV16 E7 promotes the activation of the EGFR/PI3K/AKT/NRF2 signaling pathway, in turn stimulating PIR-mediated NF-κB activation in oral cancer cells." (PMID 32679705, 2020).
osteosarcoma (2 papers, 2021 to 2022). A usually aggressive malignant bone-forming mesenchymal neoplasm, predominantly affecting adolescents and young adults. "Similarly, the mRNA levels for pirin decreased by 50% upon knockout of Nrf2 in the human osteosarcoma cell line U2OS, in which the levels of Keap1 and Nrf2 are normal." (PMID 35204145, 2022).
Parkinson disease (2 papers, 2022 to 2023). A progressive degenerative disorder of the central nervous system characterized by loss of dopamine producing neurons in the substantia nigra and the presence of Lewy bodies in the substantia nigra and locus coeruleus. "For example, it has been shown that out of 902 piRNAs expressed in somatic cells 527 are synthesized in the brain, of which piR-hsa-92056, piR-hsa-150797, piR-hsa-347751, piR-hsa-1909905, piR-hsa-2476,630, and piR-hsa-2834636 are recommended as biomarkers for Parkinson’s disease." (PMID 36531220, 2022).
serous ovarian cancer (2 papers, 2021 to 2022). "In serous ovarian cancer, piR-33733 targets LIAS3′-UTRs, whereas piR-52207 binds ACTR10 and PLEKHA5 3′-UTRs and 5′-UTRs, leading to increased anti-apoptotic and decreased pro-apoptotic proteins." (PMID 33802524, 2021).
tuberculosis (2 papers, 2023 to 2024). A chronic, recurrent infection caused by the bacterium Mycobacterium tuberculosis. "In tuberculosis (TB), the increased activity of PIWIL2 and PIWIL4, along with the significant presence of piRNAs such as piRNA-1007467, piR-hsa-1344, and piR-hsa-1944, highlights the complex involvement of the piRNA-PIWI axis in TB development." (PMID 39717847, 2024).
Allergy (1 paper, 2024). An allergy is an immune response or reaction to substances that are usually not harmful. "The specific SNPs of allergy and non-allergic groups were mainly in trafficking protein particle complex subunit 2 (TRAPPC2), Pirin (PIR), complement factor properdin (CFP), and sosondowah ankyrin repeat domain family member D (SOWAHD), however only TRAPPC2 and PIR were non-synonymous mutations." (PMID 39881721, 2024).
aortic valve calcification (1 paper, 2024). "Recently, a novel aortic valve calcification-associated PIWI-interacting RNA (piR-hsa-25624, renamed AVCAPIR) was identified in the context of increasing valvular calcification and promoting the progression of calcific aortic valve disease." (PMID 39834390, 2024).
autism (1 paper, 2025). Persistent deficits in social interaction and communication and interaction as well as a markedly restricted repertoire of activity and interest as well as repetitive patterns of behavior. "Differential piRNAs expression levels were also detected between severe and mild ASD cases, with piR-hsa-22380, piR-hsa-28131, piR-hsa-27134, and piR-hsa-27138 being the most upregulated piRNAs and piR-hsa-27623 and piR-hsa-32175 being the most downregulated piRNAs in children with severe autism." (PMID 40868063, 2025).
Autoimmunity (1 paper, 2023). The occurrence of an immune reaction against the organism's own cells or tissues. "According to our results, neutrophil, an essential immune cell in modulating autoimmunity, may have more piR-hsa-27124 and piR-hsa-25672." (PMID 37325646, 2023).
cholangiocarcinoma (1 paper, 2021). A carcinoma that arises from the intrahepatic biliary tree (intrahepatic cholangiocarcinoma) or from the junction, or adjacent to the junction, of the right and left hepatic ducts (hilar cholangiocarcinoma). "Moreover, high Pirin levels are associated with a reduced survival probability in cholangiocarcinoma patients, suggesting that Pirin is a plausible prognostic biomarker." (PMID 33557375, 2021).
colon adenocarcinoma (1 paper, 2024). "In addition, lower expression of PIR plus higher expression of FAS is correlated with the highest survival rate in colon adenocarcinoma dataset derived from Oncomine database." (PMID 38148593, 2024).
diabetic cardiomyopathy (1 paper, 2025). Diabetic cardiomyopathy is a disorder of the heart muscle in people with diabetes. "Additionally, Plin5 regulates the Pirin (PIR)/nuclear factor kappa B (NF-κB) axis to inhibit lipotoxicity and ferroptosis, providing further evidence of its protective role in diabetic cardiomyopathy and HF." (PMID 40734976, 2025).
diffuse large B-cell lymphoma (1 paper, 2021). "piR-30473 is reported to reduce WTAP mRNA attenuation and enhance mRNA stability by binding to the 3′UTR of WTAP to mediate m6A modification in diffuse large B-cell lymphoma cells." (PMID 34645714, 2021).
endometrial cancer (1 paper, 2016). Primary or metastatic malignant neoplasm involving the endometrium (mucous membrane that lines the endometrial cavity). "In contrast, we observed that OC users, who are expected to have a lower risk of developing endometrial cancer, also had a higher frequency of positive pIGF1R/pIR staining." (PMID 27125830, 2016). "The finding of a higher frequency of positive pIGF1R/pIR nuclear staining in OC users and its possible role in OC protection from endometrial cancer is a novel finding that warrants further investigation." (PMID 27125830, 2016).
fibrosarcoma (1 paper, 2021). A malignant mesenchymal fibroblastic neoplasm affecting the soft tissue and bone. "However, more studies using clinical fibrosarcoma patient samples and in vivo animal models are needed to uphold the association of piR-39980 and its two targets, RRM2 and CYP1A2, with positive responses of fibrosarcoma patients to DOX." (PMID 34799689, 2021). "Therefore, the loss of piR-39980 plays a crucial role in developing DOX resistance in fibrosarcoma cells." (PMID 34799689, 2021). "To investigate the role of piR-39980/CYP1A2 in modulating chemoresistance in fibrosarcoma, we performed an MTT assay and found that the cell viability of the DOX-treated cell was increased by 40% upon CYP1A2 overexpression (P < 0.05)." (PMID 34799689, 2021). "Our finding showed that piR-39980 could attenuate the DOX resistance by repressing the expression of RRM2 and CYP1A2 in DOX-resistant fibrosarcoma cells and hence could be a potential therapeutic agent for improving the clinical response of fibrosarcoma patients to DOX." (PMID 34799689, 2021).
head and neck cancer (1 paper, 2023). A primary or metastatic malignant neoplasm affecting the head and neck. "Longer survival of patients with head and neck cancer is associated with low levels of piR-58510 and piR-35373." (PMID 37568568, 2023).
Hypoglycemia (1 paper, 2015). A decreased concentration of glucose in the blood. "The differential pIR activities associated with the insulin and Cmpd1 combination in liver vs. peripheral tissues (i.e. higher insulin tone in liver vs. muscle) mimics endogenous insulin tissue actions, potentially contributing to reduced hypoglycemia risk." (PMID 25799496, 2015).
Hypoinsulinemia (1 paper, 2023). A decreased concentration of insulin in the blood. "In hypoinsulinemia, increased expression of pIR, Total IR, PI3K, pAKT, and Total AKT may be aimed at maintaining adequate glucose uptake for the hypertrophied myocardium to attenuate energy dysregulation in an attempt to prolong cell survival." (PMID 37047174, 2023).
Immunodeficiency (1 paper, 2022). Failure of the immune system to protect the body adequately from infection, due to the absence or insufficiency of some component process or substance. "Additionally, loss of pirin function may lead to immunodeficiency by hampering binding of p65 to DNA." (PMID 35967515, 2022). "Therefore, identification of the pathogenic variants in this protein can help in determining potential genetic factors leading to immunodeficiency and AML as well as other pathological conditions resulting for disruption of pirin function." (PMID 35967515, 2022).
infertile (1 paper, 2016). "RNA was isolated from seminal plasma samples pooled from healthy controls and infertile patients and subjected to qRT-PCR to amplify piR-31068 and piR-31925, and the amplified products were ligated into a TA vector and sequenced." (PMID 27068805, 2016).
Insulin resistance (1 paper, 2018). Increased resistance towards insulin, that is, diminished effectiveness of insulin in reducing blood glucose levels. "By contrast, there was little or no increase in the ratio of pIR/IR or pIRS-1/IRS-1 in HFD-fed mice following insulin injection, indicating central insulin resistance." (PMID 29910467, 2018).
kidney cancer (1 paper, 2023). Primary or metastatic malignant neoplasm involving the kidney. "piR-32051, piR-39894, and piR-43607 belong to the same cluster on chromosome 17, which is up-regulated in kidney cancer." (PMID 38003403, 2023).
leukemia (1 paper, 2021). A malignant (clonal) hematologic disorder, involving hematopoietic stem cells and characterized by the presence of primitive or atypical myeloid or lymphoid cells in the bone marrow and the blood. "Furthermore, Pirin is associated with contrasting high levels of peripheral white blood cells in B-precursor acute lymphoblastic leukemia, which entails a distinctive prognosis in leukemia patients." (PMID 33557375, 2021).
male infertility (1 paper, 2016). The inability of the male to effect fertilization of an ovum after a specified period of unprotected intercourse. "In this study, we have identified piR-31068, piR-31925, piR-43771, piR-43773 and piR-30198 as molecular biomarkers for male infertility." (PMID 27068805, 2016).
muscular atrophy (1 paper, 2017). The loss of muscle tissue due to inactivity or disease. "Although the functional relevance of pirin during denervation-induced atrophy is largely unknown, pirin might act as a redox sensor that activates pro-inflammatory pathways during muscular atrophy." (PMID 28546288, 2017).
neuroblastoma (1 paper, 2023). Neuroblastoma (NB) is the most common solid, extracranial childhood tumor. "Three exosomal piRNAs—hsa-piR-1040, hsa-piR-1089, and hsa-piR-1170—had a higher level in the plasma of patients with neuroblastoma." (PMID 37296747, 2023). "Additionally, hsa-piR-1089 could differentiate neuroblastoma patients from healthy controls with an AUC of 0.933." (PMID 37296747, 2023).
ocular melanoma (1 paper, 2019). A melanoma that arises from the structures of the eye or ocular adnexa. "Other tumor-related genes, such as ACAT2, PIR and CTBP1, were potentially regulated by m6A modifications in ocular melanoma." (PMID 31722709, 2019).
pancreatic ductal adenocarcinoma (1 paper, 2022). An infiltrating adenocarcinoma that arises from the epithelial cells of the pancreas. "The knockdown of PIR increased mRNA levels of ACSL4, a biomarker and a key promoter of ferroptosis, in pancreatic ductal adenocarcinoma cell lines." (PMID 36467089, 2022).
papillary thyroid cancer (1 paper, 2023). "The piRNA sequencing data of papillary thyroid cancer revealed two upregulated piRNAs, piR-13,643 and piR-21,238, showing better specificity than the current biomarker HBME1 in distinguishing benign and malignant nodules and were closely related to prognosis." (PMID 38031146, 2023).
parasitic infection (1 paper, 2024). "PIR genes comprise one of the largest multigene families in Plasmodium, with their expression indicative of blood-stage parasitic infection but not necessarily playing a role in antigenic variation." (PMID 38584870, 2024).
postmenopausal osteoporosis (1 paper, 2021). Metabolic disorder associated with fractures of the femoral neck, vertebrae, and distal forearm. "Additionally, it shows that piR-63049 inhibition may be considered as a novel and viable approach for the prevention and treatment of bone loss disorders, such as postmenopausal osteoporosis." (PMID 34803507, 2021).
pulmonary hypertension (1 paper, 2023). Increased pressure within the pulmonary circulation due to lung or heart disorder. "piR-63,076 knockdown attenuated the development of pulmonary hypertension by inhibiting the proliferation of PASMCs, implicating its potential role as a biomarker and a therapeutic target for pulmonary hypertension." (PMID 38031146, 2023).
renal carcinoma (1 paper, 2025). A carcinoma arising from the epithelium of the renal parenchyma or the renal pelvis. "Finally, we construct a biomimetic nanoparticle system to achieve the renal cancer‐specific targeted delivery of piR‐RCC, and offer a promising therapeutic avenue for RCC." (PMID 40411401, 2025).
skin cancer (1 paper, 2022). "A number of studies have documented the tumour-promoting roles of pirin in human cervical, lung, oral, and skin cancers, and have been recently reviewed." (PMID 35204145, 2022).